IL10 (interleukin 10)
Diseases named in the same sentence as IL10 in open-access papers (continued):
Sharing a sentence is not in itself a finding about the gene and the disease.
tumor (continued). "On the contrary, tumor cell-derived paracrine signals contribute to M2-like macrophages, including IL-10, CSF-1, different chemokines (CCL2, CCL18, CCL17, and CXCL4), and various extracellular matrix components." (PMID 32653013, 2020). "Tumor cells-macrophage co-culture increases expression of IL10, IL12, IL6, TNF, CCL5, CCL22, and CSF1 in macrophages, thereby inducing M2-like polarization." (PMID 32219066, 2020). "Nevertheless, our data confirmed an elevated IL-10 expression in tumor tissue from patients with PTC with concomitant HT both by qPCR and IHC staining." (PMID 32348468, 2020). "In gliomas, upregulation of PD-L1 expression in circulating monocytes and tumor infiltrating macrophages yield an immunosuppressive phenotype by regulating autocrine/paracrine IL-10 signaling." (PMID 32944395, 2020). "A better understanding of LAP as an influential driver in this regard is crucial to discover a novel approach to block the immunosuppressive and pro-tumor effects of IL-10 for effective clinical management of tumors." (PMID 32850405, 2020). "They stimulate regulatory T cell differentiation and secrete several factors (e.g., TGFβ, TNFα and IL-10) to create a favorable environment for tumor progression and to inhibit the anti-tumor effects of immune cells." (PMID 32344813, 2020). "The treatment of released AP moiety increased the expression of IL-2, while that of IL-10 was decreased, showing potential in restoring Th1/Th2 immune balance in tumor microenvironment." (PMID 32646040, 2020). "We conclude that a novel function of thymically-expressed IL-10 in the tumor-bearing host diverts T-cell differentiation toward a DC pathway, thus limiting the protective adaptive immune repertoire." (PMID 32582141, 2020). "In macrophages, adenosine induces pro-tumor M2 macrophage polarization by reducing the expression of IL-2, TNFα, and nitric oxide but upregulating arginase-1, IL-10, and VEGF." (PMID 32775303, 2020). "Both IL-2 and IL-10 were found to increase the cytotoxic activity of anti-tumor CD8+ T cells in vitro, suggesting a potential synergistic effect for the two cytokines." (PMID 32013102, 2020). "Subsequently, we further confirmed that M2 macrophages (CD163 +) were enriched in human ICC tissues and secreted IL-10 to exert their tumor-promoting effects." (PMID 33372604, 2020). "IL-10 injection in mice was shown to enhance anti-tumor immunity immediately after DC vaccine administration." (PMID 33374342, 2020). "We confirmed the relationship between IL-10 expression and T-reg abundance, which was significantly higher in the culture supernatant of T-regHi tumor samples than in the T-regLo ones (p < 0.05)." (PMID 32554190, 2020). "On the contrary, Th2 cells secrete pro-tumoral cytokines, such as IL-4, IL-5, IL-6, IL-10, and IL-13, which induce anergy in T cells and promote the activities of tumor-promoting macrophages." (PMID 33322132, 2020). "Characterized by their hallmark cytokines, IL-10 and TGF-β, which can effectively suppress tumor-specific T cell activation, Tregs are attracted to the local tumor environment by soluble mediators, such as CCL22 or CCL2 produced by glioblastoma cells." (PMID 32117316, 2020). "IL-10 plays a crucial role in dampening anti-tumor immunity by suppressing the activity of different immune cells, eventually leading to the inactivation of effector T-cells." (PMID 33212945, 2020). "In other cases, macrophages with the M2 phenotype prevent the activation of T lymphocytes through the production of mediators such as IL-10 and prostaglandin E2 and promote tumor growth through the secretion of TGF- β and VEGF." (PMID 32225076, 2020). "Data from experiment settings link overexpression of IL-10 to the LAP pathway and implicate this association in LAP-mediated tumor progression." (PMID 32850405, 2020). "The early surge of IL-10 following pleurodesis accompanied by a longer survival suggests an anti-tumor effect of IL-10." (PMID 33322487, 2020).
tumor (continued). "This phenotype that leads to tumor progression is associated with large amounts of proangiogenic factors such as VEGF, IL-10, TGF-β, PGE2 and also recruits a greater number of Tregs to tumor areas." (PMID 32636725, 2020). "Various types of cancers and cytokines compose the TME, including tumor cells, immunosuppressive cells, stromal cells, IL-6 and IL-10, to name a few, which collectively form a complex of immunosuppressive network." (PMID 32117960, 2020). "TIM-3 blockade in tumor infiltrating Tregs induced the expression of IL10, a cytokines involved in T-cell exhaustion." (PMID 32937953, 2020). "On the other hand, previous studies have described that IL-10 deficiency leads to elevated levels of TNF-alpha, IL-6, and IL-17, triggering chronic inflammation and promoting tumor growth." (PMID 32947866, 2020). "We evaluated the plasma concentrations of Th1 (IL-2, IFN-γ, and TNF-α), Th2 (IL-4, IL-5, IL-6, and IL-10), Th9 (IL-9), and Th17 (IL-17A, IL-17F, IL-21, and IL-22) cytokines in tumor-bearing mice by flow cytometry." (PMID 32802733, 2020). "The concentration of IL-10 in the blood as well as in tumor microenvironment would be crucial in the process of tumorigenesis." (PMID 32684831, 2020). "Recently, several studies have reported that regulatory cytokines in the TME, such as interleukin (IL)-10 and IL-35, support tumor development via the suppression of antitumor immunity in cancer." (PMID 32973297, 2020). "Neutrophils can exert tumor-promoting activity by secreting a variety of inflammatory mediators, including vascular endothelial growth factor, interleukin (IL)-6, IL-10, and IL-22." (PMID 32528232, 2020). "IL-10 can also trigger the generation and activation of Treg cells, all of which can limit anti-tumour immune responses, leading to cancer disease progression." (PMID 32931721, 2020). "DPTs at tumor sites secrete more IL-10, IDO, and TGFβ and express higher levels of immune checkpoints PD-1, LAG-3, and TIM-3 than Tregs, CD4+ T cells and CD8+ T cells." (PMID 32457755, 2020). "More knowledge about how inflammation or tissue specific tolerance for tumor proliferation will be helpful to determine using recombinant IL-10 or anti-IL-10R Ab to fight against cancer." (PMID 32670290, 2020). "Pegylated IL-10 had been developed and demonstrated as an effective anti-tumor immune response with long-lasting immunologic memory." (PMID 33322487, 2020). "In the CIN group, the concentrations of IL-8, IL-10, and nitric oxide in cervicovaginal secretions were higher than those in the control group, indicating that these mediators play a role in the tumor immune microenvironment." (PMID 33425785, 2020). "Anti-inflammatory cytokine IL-10 can generate alternatively-activated macrophages that support tumor growth." (PMID 33003428, 2020). "Fibroblasts are transformed to TAFs by cytokine signaling in tumors, such as TGF-β and IL-10, which results in cancer progression and hinders tumor-specific immunity." (PMID 32424240, 2020). "In vitro studies have shown that the suppression of IL-10 can promote an anti-tumor immune response in CLL patients." (PMID 33375215, 2020). "This cytokine binds to colony stimulating factor 1 receptor (CSF-1R) in the monocytes, directing their transformation toward the M2 phenotype and stimulating the secretion of anti-inflammatory, tumor-promoting factors IL-10 and TGF-β." (PMID 32477352, 2020). "Of note, TAMs directly participate in CCL-2 and IL-10 production, suggesting the existence of an autocrine amplification loop involved in their tumor-related recruitment and polarization." (PMID 33212945, 2020). "CD31 immunohistochemistry and alginate encapsulation experiments showed tumor angiogenesis were inhibited in MSCs-IL10 group in comparison to the control and vector group (P < 0.001), FITC-labeled dextran intake was also lower than the other groups (P < 0.01)." (PMID 32742480, 2020).
tumor (continued). "Through IL-10 and IL-35 cytokine production, tumor-infiltrating Tregs help tumor cells escape immune surveillance." (PMID 33479597, 2020). "Overall, these data show how TAM polarization via IL10 locally shapes neighboring tumor cells to promote behaviors that distinguish in vivo MT dynamics from their in vitro counterparts." (PMID 32665556, 2020). "In some settings depending on the type of tumor, MCs can have an immunosuppressive role by releasing IL-10, histamine, and TNF-α." (PMID 31256327, 2020). "This process is driven by increased thymic production of IL-10 under tumor condition, which acts on IL-10Rhigh DN2 cells by promoting DC lineage commitment (with assistance from CD45−keratin5high thymic stromal cells)." (PMID 32582141, 2020). "Recent advances in tumor immunology demonstrate that tumor-infiltrating B cells influence tumor progression through the productions of antibodies, immunosuppressive cytokines such as IL-10, as well as by interacting with other immune cells." (PMID 33333768, 2020). "In this study, in the orthotopic-mice model of HCC, YPF increased the levels of Th1 cytokines (IL-2, IL-12, TNF-α, and IFN-γ), decreased the levels of Th2 cytokines (IL-4, IL-5, IL-10, and IL-13), and increased the Th1/Th2 ratio in tumor and adjacent tissues." (PMID 32351590, 2020). "This study suggests that CD4+CD25+CD127lowTregs, TGF-β1, IL-10 are closely related to the occurrence and development of tumor." (PMID 32218692, 2020). "For our study, we cross‐bred MSH2loxP/loxP Vil‐cre mice into the IL‐10−/− background to study the relevance of inflammation, intestinal tumor localization and bacterial proximity as important cofactors for tumor development under mismatch repair deficiency." (PMID 32350866, 2020). "Later on, a study isolated TAMs derived from primary lung cancer tissues and found a strong correlation between increased IL-10 and stage, tumor size, lymph node metastasis, and lymphovascular invasion in non-small cell lung cancer patients." (PMID 32326073, 2020). "IL-10 leads to tumor growth and promotion, but it also contributes to the eradication and suppression of cancer development under colonic inflammatory conditions." (PMID 32670290, 2020). "In a breast cancer model, supernatant from infiltrating γδ T cells suppresses the proliferation of anti-tumor CTLs in an IL-10-dependent manner." (PMID 33042132, 2020). "More importantly, evidence showed that IL-10 effectively induced activation of CD8+ T cells in several mouse tumor models, suggesting its therapeutic potential in cancer immunotherapy." (PMID 32348468, 2020). "In cancer, the immunomodulatory cytokine IL-10 is proposed to induce anti-tumor immune stimulation and tumor-promoting immunosuppression in a context-dependent manner, making it an attractive target for cancer therapy." (PMID 32724474, 2020). "Many studies have reported upregulated serum IL‐10 levels and higher expression of IL10 gene in tissues of patients with HCC compared to non‐tumor status." (PMID 32537885, 2020). "During chronic inflammation, the cytokines tumor necrosis factor (TNF-α), interleukin 6 (IL-6), transforming growth factor β (TGF-β), and interleukin 10 (IL-10) have been shown to be involved in tumor induction, proliferation, and metastasis." (PMID 33023215, 2020). "In tumor tissue, IL10 expression levels missed a significant correlation with patient survival by a small margin." (PMID 32100077, 2020). "It is a polyergic immunoregulatory cytokine that belongs to the IL-10 gene family, with a wide range of antitumor properties, including specific induction of tumor cell apoptosis, inhibition of tumor angiogenesis, and regulation of antitumor immune responses." (PMID 33014054, 2020). "For example, cytokines IL-4 and IL-10 secreted by tumor cells or T cells can polarize macrophages to their M2 state in which they are capable of secreting TGF-B1 and CXCL12 to inhibit CD8+ T cell function in support of tumor cell survival and metastasis." (PMID 31979136, 2020).
tumor (continued). "Macrophages were generated by either polarizing them in the presence of the M2 cytokines IL4 (M2(IL4)) or IL10 (M2(IL10)) or in the presence of tumor-cell conditioned medium (TAM-like)." (PMID 32438733, 2020). "IL-10 can inhibit cytotoxicity mediated by helper T cells and NK cells and stimulate tumor immune tolerance, thereby inhibiting antitumor immune responses and accelerating tumor progression." (PMID 32669133, 2020). "Tumor microenvironment of hepatic, gastrointestinal, and breast cancer contains high levels of tumor-suppressor cells such as MDSCs which generate various cytokines such as IL-10 for the activation of Tregs and inhibition of other immune cells." (PMID 32377541, 2020). "Patients with lower age (P <0.001), T1/T2 grading (P < 0.001), N0 grading (P < 0.001), tumor size less than 5 cm (P < 0.001), and low PD-L1 expression (P < 0.001) presented with lower IL10 expression levels." (PMID 32724815, 2020). "TNFα, MCP-1 and IL-10, which we previously reported to be enhanced in the tumour microenvironment following systemic IgE treatment in vivo, were secreted by monocytes alongside immune mediators CXCL-10, IL-4, IL-1β and IL-23." (PMID 33203088, 2020). "Compared to those on CD4+ T cells in PBMCs, the expression levels of antitumor (TNFβ, T-bet, and granzyme B) and protumor (PD-1 and IL-10) markers on CD4+ T cells in tumor sites were commonly higher." (PMID 32117733, 2020). "More extensive and higher intensity of IL-10 staining can be seen on tumor samples with PTC + HT compared with PTC." (PMID 32348468, 2020). "For instance, knockdown of semaphorin 4D, a pro-angiogenic factor overexpressed in many malignancies, in tumor cells reduces the IL-10 production by MDSCs." (PMID 32793192, 2020). "We showed that Etanercept reduces the transcript levels of TNF-α, IL10 and CCL22, all of which are associated with tumor progression." (PMID 32883235, 2020). "In tumour progression, Tregs produce the inhibitory cytokines interleukin 10, transforming growth factor β and haemoglobin oxygenase 1 to achieve immune escape." (PMID 32758195, 2020). "As an immunosuppressive factor, IL-10 can inhibit not only the apoptosis of tumor cells but also the role of IFN-γ and the anti-tumor immune response." (PMID 32942998, 2020). "Patients with lower age (P = 0.048), high tumor differentiation (P = 0.001), T1/T2 staging (P < 0.001), low IL10 expression (P < 0.001), and low CD8 expression (P = 0.023) exhibited lower PD-L1 expression levels." (PMID 32724815, 2020). "With regard to plasma chemokine levels, IL-1β was increased in females and IL-10 was increased in males, more markedly in the males with tumor." (PMID 32545680, 2020). "In HCC, PD-1hi B cells induce T cell dysfunction through the IL10-dependent pathway, thereby creating conditions conducive to tumor progression." (PMID 32944395, 2020). "WNT3A derived from GBM induces upregulation of stress-inducible protein 1 (STI1/HOP), interleukin 10 (IL-10), and arginase-1 (ARG-1) in tumor-associated microglia." (PMID 33312955, 2020). "In this way, IL-10 has more ways to help malignant lymphocytes express genetic material, achieve the purpose of reproduction, and promote immune escape of tumor." (PMID 33154947, 2020). "High levels of serum IL-2, IL-10, and IL-12 are correlated to the aggressive tumor characteristics in patients with DTC." (PMID 32655554, 2020). "In particular, anti-inflammatory cytokine interleukin-10 (IL-10) was shown to be highly enriched in HCC tumors as compared to adjacent non-tumor or healthy liver tissues." (PMID 33117354, 2020). "We next applied macrophage-conditioned supernatants to renal tumor cells CAKI-1 and 786-O and observed enhanced proliferation as well as tumor cell migration measured by xCELLigence in real-time upon stimulation with IL-10-conditioned media." (PMID 32106629, 2020). "Conversely, IL-10 acts as an immunosuppressant, decreasing the antitumor response of T cells, thereby facilitating tumor proliferation." (PMID 32660099, 2020).
tumor (continued). "INF-γ and IL-10, which are anti-tumor and anti-inflammatory cytokines, were increased in the probiotic group but were decreased or unchanged in the placebo group." (PMID 32664289, 2020). "(vii) TAMs induced autocrine IL10 signaling pathway drives M2-like TAMs polarization to suppress anti-tumor response in TME." (PMID 32219066, 2020). "Such upregulation of FasL in tumor endothelium is stimulated by the secretion of some factors by cancer cells including interleukin-10 (IL-10), prostaglandin E2, and vascular endothelial growth factor-2 (VEGF-2)." (PMID 32212814, 2020). "They differentiate from circulating monocytes after migrating into tumor tissue upon stimulation with IL-4, IL-10, or IL-13 and exhibit pro-tumorigenic functions." (PMID 32184778, 2020). "At tumor sites, immunosuppressive cytokines, such as TGFβ, IL-10, and IL-6, are produced by immunosuppressive cells." (PMID 32731404, 2020). "Mostly, IL-10 is regarded as an immunosuppressive, anti-inflammatory cytokine, which promotes tumor escape from immune surveillance." (PMID 33042814, 2020). "Some other studies have also showed that IL-10 can be produced by tumor cells themselves, and indicating that its expression is an escape mechanism from immune surveillance." (PMID 33614473, 2020). "Analyses of gene profiles from Tconv cells that had been exposed to these Treg subtypes proposed that IL-35+ Tregs promoted Tconv exhaustion whereas IL-10+ Tregs repressed anti-tumor effector functions of Tconv cells." (PMID 33375291, 2020). "Li and colleagues demonstrated that TAMs-secreted IL-10 promotes cancer stem cell-like properties and tumor growth in NSCLC; High levels of IL-10 are associated with a poor prognosis of NSCLC patients." (PMID 32117960, 2020). "In melanoma tumor immunity, B1a cells negatively regulate anti-tumor immunity by producing IL-10, suggesting they can be a target for immunotherapy of tumor." (PMID 32973780, 2020). "In the context of cancer, MDSCs and IL-10 can inhibit anti-tumour immune responses, thereby leading to tumour progression." (PMID 32931721, 2020). "Conversely, IL-10 contributes to tumor growth by inducing an immune response and an anti-inflammatory microenvironment that promotes tumor escape from immune surveillance." (PMID 32733470, 2020). "Fruti treatment increased ROS, N-acetyl-β-D-glucosaminidase (NAG) and TNF-α levels in tumor tissue by 15, 29 and 79%, respectively, and reduced IL-10 by 68%, compared to vehicle group." (PMID 33020521, 2020). "Oncogenic MAPK signaling results in the production of immunosuppressive factors (e.g., VEGF, IL-6 and IL-10), which inhibit the proliferation and activation status of tumor-specific T cells and DCs." (PMID 32290124, 2020). "Transforming growth factor-β (TGF-β) and IL10 produced by tumor cells and immune cells of TME can inhibit NKG2D expression." (PMID 32582698, 2020). "Level of IFN-γ significantly rose and TGF-β and IL-10 levels were significantly reduced in tumor tissues and blood from DCTEX-N1ND-treated mice, compared with DCTEX and PBS groups." (PMID 32286296, 2020). "IL-10 is usually produced when tumor cells are stimulated by M2 macrophages, which in turn can promote the transformation of macrophages to the M2 phenotype." (PMID 33511267, 2020). "MDSCs are a major source of IL-10 in tumor-bearing host, and consistently, the frequency of MDSCs is correlated with the IL-10 level in peripheral blood of cancer patients." (PMID 32793192, 2020). "The maturation of invasive DCs is influenced by many factors, including the secretion of VEGF, TGF-beta, PGE2, eNOS, and IL-10 by tumor cells." (PMID 32754587, 2020). "We focus on the killing effect and mechanisms of macrophages on tumors, while tumor promoting factors such as IL-6, IL-8, IL-10, TLR4 are briefly introduced as well." (PMID 32161718, 2020).